ABO (ABO, alpha 1-3-N-acetylgalactosaminyltransferase and alpha 1-3-galactosyltransferase)
Diseases named in the same sentence as ABO in open-access papers (continued):
Sharing a sentence is not in itself a finding about the gene and the disease.
malaria (continued). "Disease phenotypes such as rosette formation are thought to be influenced by the ABO blood group, where by O individuals being lower risk of severe malaria while group A are more predisposed individuals to severe malaria." (PMID 30906890, 2019). "The association between ABO and malaria has been investigated extensively in the past, and these studies have consistently shown that Group O is associated with protection against severe malaria." (PMID 29802282, 2018). "This is consistent with another series that indicated a strong association between blood ABO group with asymptomatic malaria P=0.022 and a high rate of parasitaemia in blood group O; P=0.003." (PMID 30112007, 2018). "While all ABO alleles are globally distributed, the frequency of blood type O is generally higher in malaria endemic areas, being at high frequencies in much of sub-Saharan Africa and nearly ubiquitous in South America18." (PMID 29802282, 2018). "Studies on the association between ABO blood types and malaria among Chinese adults are extremely rare." (PMID 29238723, 2017). "The relationship between ABO blood types and malaria susceptibility has been studied by several researchers; however, the results have been contradictory." (PMID 29238723, 2017). "Among the global malaria burden, 90% has been estimated to occur in Sub-Saharan Africa; hence, research on the association between ABO blood types and malaria has been concentrated in Africa." (PMID 29238723, 2017). "This study was aimed at investigating the role of ABO blood types on malaria risk among the Chinese people." (PMID 29238723, 2017). "Facility based cross-sectional study was conducted from February to June, 2015, to assess ABO/Rh blood groups distribution and their association with asymptomatic malaria." (PMID 26925291, 2016). "Our study is the first to comprehensively survey important malaria candidate polymorphisms (including HbS and ABO) in a Brazilian population from the Medium Negro River Basin in the Amazon." (PMID 22615793, 2012). "Here we test a panel of 65 SNPs, previously linked to altered risk of malaria or other infectious diseases, including the HbS and ABO polymorphisms, for association with severe malaria, and with the various clinical presentations of severe malarial disease." (PMID 23144702, 2012). "To determine if ABO polymorphism influences malaria parasite invasion and maturation, we examined P. falciparum (ITG clone) parasite invasion and development in A, B, and O erythrocytes in vitro." (PMID 23071435, 2012). "Previously we had demonstrated the association of ABO blood group with severe malaria in Odisha population." (PMID 23152904, 2012). "Despite these limitations in understanding of cause effect relationship, CR1 polymorphisms and ABO blood group system appear to affect the outcome of P.falciparum infection in malaria endemic areas." (PMID 23152904, 2012). "Several associations have been reported between the ABO blood group phenotype and relative risk of infectious diseases, including malaria." (PMID 22807674, 2012). "The association of ABO blood group in different clinical phenotypes of severe malaria, categorized as CM, NCSM and MOD, was studied." (PMID 22011404, 2011). "This study analyses the association between ABO blood group phenotypes in relation to placental malaria pathology and birth outcomes in southern Malawi, an area with perennial malaria transmission." (PMID 17683546, 2007). "In the present study we sought to confirm if the association of ABO phenotype and malaria related outcome in pregnancy also occurred in women living under conditions of perennial malaria transmission in Malawi." (PMID 17683546, 2007). "This study analyses the association between ABO blood group phenotypes in relation to placental malaria pathology." (PMID 16916459, 2006).
malaria (continued). "Transfusion-transmitted infections (TTIs) such as HIV, HBV, HCV, syphilis, and malaria pose significant risks to blood safety.Therefore, it is of interest to assess the seroprevalence of TTIs and their association with ABO/Rh blood groups among 30,335 blooddonors." (PMID 41170087, 2025). "We conducted an eight-month study (October 2024 - May 2025) with 749 Moroccan soldiers to investigate if their ABO and Rh blood groups played a role in their risk of contracting malaria, how often they got it, or if they developed severe forms." (PMID 40821228, 2025). "Case-control analysis of the association between ABO genotype and severe malaria syndromes." (PMID 37708213, 2023). "Here, we used a case-control study conducted in East Africa to investigate whether specific ABO genotypes are associated with differing levels of susceptibility to severe childhood malaria." (PMID 37708213, 2023). "Hence, a direct causal link between host ABO genotype, parasite virulence in terms of rosette size, and the primary pathological process of microvascular obstruction in severe malaria is suggested." (PMID 37708213, 2023). "To determine whether ABO genotype might influence malaria susceptibility via these mechanisms, we conducted in vitro experiments examining cytoadhesion to ICAM-1 and CD36 and PfEMP1 display in relation to infected RBC ABO genotype." (PMID 37708213, 2023). "Babesia divergens is an intraerythrocytic parasite with many similarities to malaria, but the impact of ABO on the susceptibility to and progression of the infection in humans is unknown." (PMID 37375493, 2023). "We also investigated whether ABO genotypes are associated with risk of uncomplicated malaria or asymptomatic infection in a longitudinal cohort and cross-sectional study, respectively." (PMID 37708213, 2023). "In addition, the ABO blood group has previously been linked to susceptibility to other diseases, such as influenza, malaria, schistosomiasis, and SARS-CoV-2." (PMID 35455670, 2022). "These inconsistencies maybe be due to geographic and ethnic distribution of the different ABO genetic blood polymorphisms associated with malaria protection in the regions." (PMID 32646433, 2020). "Considering the consequences of placental malaria in terms of infant mortality, the influence of the ABO polymorphism on malaria in pregnancy may contribute to the high frequencies of the O allele in sub-Saharan Africa." (PMID 25066505, 2014). "Here we investigate whether a number malaria candidate SNPs, including the HbC, HbS and ABO, are associated with severe malaria." (PMID 22957039, 2012). "Therefore, the current study aims to investigate this association and look into the overall role of ABO blood group in risk/resistance to the development of severe malaria by a meta-analysis of results from the current study and earlier published reports." (PMID 22011404, 2011). "Severe malaria GWASs have replicated some of the well-known variants such as HbS and ABO blood groups and few novel variants related to red blood cell membrane biology which reinforce the importance of erythrocyte variants for protection against severe malaria." (PMID 31409341, 2019). "Hence the aim of the present study was to assess the ABO/Rh blood group distribution and association with asymptomatic malaria among blood donors attending Arba Minch Blood Bank, South Ethiopia, where malaria is one of the most important public health problems." (PMID 26925291, 2016). "However, the association between HbS rs334 and ADCY9 rs2230739 with plasma levels of transforming growth factor-beta as well as ABO rs8176746 with interleukin-10 is quite interesting since resistance to severe malaria has been linked to the ability to produce these immuno-regulatory cytokines." (PMID 24934404, 2014).
malaria (continued). "This work identifies the interaction with the ABO group as pivotal in rosetting and associates, for the first time, P. falciparum rosetting with the A subgroups, consistent with a contribution of virulent malaria to the selection of ABO blood group polymorphisms." (PMID 22807674, 2012). "While previous studies have suggested an association between ABO and severity, we document for the first time an increased odds ratio of death associated with A or AB types, providing clinical evidence to substantiate malaria as an evolutionary driver of human ABO blood group distributions." (PMID 22909232, 2012). "The association between the ABO groups, rosetting and severe malaria is a strong indication that rosetting, as a contributor to severe malaria, has exerted a selective pressure that has shaped population polymorphisms at the ABO locus and has contributed to their varying geographic distribution." (PMID 22807674, 2012). "Our study, conducted among a Moroccan military contingent deployed in the CAR, aimed to evaluate the influence of ABO and Rh blood groups on various aspects of malaria: disease incidence, recurrence of episodes, and severity." (PMID 40821228, 2025). "Substantial evidence suggests that the origin, distribution, and relative proportions of human ABO blood types are influenced by selective genetic pressure from malaria parasite infection, particularly in malaria-endemic regions." (PMID 40993672, 2025). "Numerous research studies have been conducted to determine how an individual's ABO blood type influences distinct kinds of malaria." (PMID 39371587, 2024). "The results herein provide evidence for the association of TLR4 and related genes, ICAM1, IFNGR1, IL13, and IL6, as well as ABO, with the incidence of clinical malaria." (PMID 37287037, 2023). "The susceptibility difference and parity-specific associations of ABO phenotypes with placental malaria might be due to the effect of the ABO phenotype on the level of the proteoglycan thrombomodulin, which is present in the placenta and mediates the binding of malaria-infected RBCs with CSA." (PMID 38037059, 2023). "A total of 366 samples from an ongoing malaria surveillance study were diagnosed for malaria by microscopy and further typed for blood group using ABO blood grouping." (PMID 36050680, 2022). "Several other genes with genetic variants associated with resistance to malaria (e.g. HBB, ABO) are under balancing selection." (PMID 34449765, 2021). "Genetic diversity of ABO blood, glucose-6-phosphate dehydrogenase (G6PD) deficiency and haemoglobin type and their ability to protect against malaria vary geographically, ethnically and racially." (PMID 32646433, 2020). "All pregnant women that were positive for malaria were also tested for ABO blood groups and genotype." (PMID 29861750, 2018). "Recently, determination of ABO group ratio in the residents as well as ABO group preference of malaria vectors in two malaria-endemic areas in south of Iran using mtDNA-cytB PCR-RFLP revealed the high prevalence of O group in this region." (PMID 30069199, 2018). "We therefore believe that rather than being contradictory, these data uncover for the first time the complex co-evolutionary landscape behind the interaction between malaria and the ABO blood group." (PMID 29802282, 2018). "The ABO locus has the previous indication of a protective effect conferred by the blood group O against severe malaria." (PMID 29868223, 2017). "The relationship between ABO blood types and malaria was first suggested over 50 years ago, and new information have since emerged, with the prevailing controversies." (PMID 29238723, 2017). "Our study aimed to understand the relationship between ABO/rhesus blood systems and malaria prevalence among University students of the University of Dschang attending the Faculty of Science Open Door Day (FSODD)." (PMID 38601352, 2016).
malaria (continued). "Plasmodium falciparum malaria has long been suggested to influence the global distribution of the ABO blood groups, similar to the selection of the malaria-protective sickle cell gene in endemic regions." (PMID 25066505, 2014). "In contrast, findings are notably ambiguous with respect to the impact of the ABO system on malaria in pregnancy." (PMID 25066505, 2014). "Accordingly, the different prevalence of ABO group genotypes among the populations has been demonstrated to be driven by malaria selection." (PMID 25512760, 2014). "Further studies in areas of different endemicity using Plasmodium PCR will be needed to elucidate the role of ABO blood groups in acquiring infection and the outcome of disease in malaria." (PMID 23706132, 2013). "It is significant that malaria resistance genes are often extremely variable, for example, the malaria resistance genes ABO, G6PD, HLA, α-globin, and β-globin, are some of the most variable human genes." (PMID 23088866, 2012). "Recent evidence suggests that the ABO blood group system has also been subject to malaria-related selection pressure." (PMID 23071435, 2012). "In Plasmodium falciparum infection, complement receptor-1 (CR1) on erythrocyte’s surface and ABO blood group play important roles in formation of rosettes which are presumed to be contributory in the pathogenesis of severe malaria." (PMID 23152904, 2012). "That malaria is likely to be changing global distributions of ABO types is supported not only by our severity or survival associations, but also by the large differences noted between our SM cases and healthy Ugandan adult blood donors." (PMID 22909232, 2012). "This is the first study to examine the relationship between ABO blood group phenotype in women prospectively and actively followed for malaria (P. falciparum and P. vivax) during pregnancy." (PMID 22826494, 2012). "In contrast, the death toll from malaria is highest in children and plasmodial parasites invade erythrocytes, the very cells that express the ABO antigens on their surface." (PMID 21513504, 2011). "The role of ABO blood group in malaria has been investigated in various populations, but robust data is limited." (PMID 22011404, 2011). "This study aims to evaluate the relationship between ABO blood group and severe malaria in an adult population at the tertiary care centre in Odisha." (PMID 22011404, 2011). "Therefore, identifying ABO phenotypes could help to detect those children at high risk for malaria." (PMID 22187584, 2011). "The study aimed to investigate the role of ABO blood groups on pregnancy outcomes in an area of unstable malaria transmission in eastern Sudan." (PMID 17692119, 2007). "This phenomenon may be related to the influence of ABO genotypes on malaria parasite clustering, with the O blood type reducing the size and stability of malaria parasite-host RBC rosettes compared to non-O blood types." (PMID 40993672, 2025). "However, the possible relationship between ABO antigens and diseases, including malaria, has been recognized." (PMID 39722561, 2024). "Furthermore, the relationship between malaria and the ABO blood group should be evaluated taking into account the minor ABO blood group, allelic frequency, and genotypic frequency of the ABO blood type." (PMID 39371587, 2024). "Additional studies examining the effects of ABO genotype, as well as weak A and B blood groups, may give further insights into the complex host-parasite interactions in severe malaria." (PMID 37708213, 2023). "Analysis of the role of ABO blood group antigens in malaria pathogenesis is complicated by the many other endothelial receptors known or suspected to be involved in sequestration, and by the high number and diversity of the parasite molecules that serve as sequestration ligands on IEs38." (PMID 32732983, 2020).
malaria (continued). "This is in line with some publications reporting that endemic malaria seems to protect from COVID-19 outbreak and that genetic variations associated with malaria (e.g., ACE2 and ABO genes) may play protective roles." (PMID 32423094, 2020). "Therefore, it was imperative to investigate the effect of ABO, G6PD and haemoglobin variants on highland malaria in Kenyan children resident in western Kenya." (PMID 32646433, 2020). "However, in view of the global distribution of the ABO(H) blood groups, an evolutionarily selective infectious disease like malaria appears to be the major reason." (PMID 29754430, 2018). "The presence of naturally acquired antibodies, impact on rosetting rate, surface reactivity and opsonization for phagocytosis in relation to different blood groups of the ABO system were assessed in a set of sera from children with mild or complicated malaria from an endemic area." (PMID 29459776, 2018). "ABO blood group, USP38, FREM3 and alpha-thalassemia have previously been putatively associated with severe malaria in a Tanzanian population, but these associations are no longer statistically significant (P>10−4) at a more stringent GWAS significance threshold." (PMID 29381699, 2018). "Therefore, this study aims to determine the relationship between ABO blood types and malaria among adults in east China." (PMID 29238723, 2017). "Future studies alluding to their involvement in other aspects of malaria pathology could yield further insights into the role of malaria in shaping population genetics beyond that of the ABO blood groupings." (PMID 28233866, 2017). "Second, malaria patients in this study were concentrated in the Zhejiang Province; the data may be insufficient to evaluate the relationship between ABO blood types and malaria in east China." (PMID 29238723, 2017). "There is also a hypothesis that Plasmodium falciparum (P. falciparum) malaria has shaped the distribution of ABO blood groups in humans." (PMID 26925291, 2016). "The B-determining allele at the ABO locus showed a positive environmental correlation with malaria that was significant (P < 0.05) without adjusting for population structure." (PMID 26744416, 2016). "Recent efforts at elaborating a genetic architecture of malaria have focused on severe malaria, leading to the identification of two new genes and confirmation of previously known variants in HBB, ABO and G6PD, by exploring the whole human genome in genome-wide association (GWA) studies." (PMID 25887595, 2015). "The determination of ABO type, an unchanging attribute and a categorical measure of the host, is of particular appeal because of its ease of testing in resource-limited settings, and its significance at the level of malaria mortality." (PMID 22909232, 2012). "Notably, four of the associated loci (ABO, HBB, DARC and CR1) have been implicated in resistance to malaria, a disease endemic in Sardinia until a few decades ago." (PMID 22291609, 2012). "Several studies have examined the effects of the ABO group phenotype on malaria risk in non-pregnant subjects and this evidence has recently been reviewed." (PMID 17683546, 2007). "Overall, the data show that ABO genotype influences P. falciparum rosetting and support the hypothesis that double dose non-O genotypes confer a greater risk of severe malaria than AO/BO heterozygosity." (PMID 37708213, 2023). "Similarly, few studies have been conducted which have examined the association between ABO genotype (rather than phenotype) and malaria susceptibility, or potential protective mechanisms such as their impacts on rosetting." (PMID 37708213, 2023). "Although associations between ABO blood group, P. falciparum rosetting and susceptibility to severe malaria are well-established, to the best of our knowledge, higher resolution analyses to determine their associations with distinct ABO genotypes have not been conducted." (PMID 37708213, 2023).